USP25 (ubiquitin specific peptidase 25)
Diseases named in the same sentence as USP25 in open-access papers (continued):
Sharing a sentence is not in itself a finding about the gene and the disease.
bacterial infection (4 papers, 2021 to 2024). "They assumed that the down-regulated USP25/HDAC11 axis mediated by CSE might contribute to the high susceptibility of the smoking population to bacterial infections." (PMID 34249948, 2021). "USP25 is also involved in the immune regulation of colon tumors and intestinal bacterial infections by regulating the levels of Wnt and suppressor of cytokine signaling 3 (SOCS3)." (PMID 35096833, 2021). "USP25, a ubiquitin-specific protease, plays a role, besides others, in bacterial infection." (PMID 37841261, 2023). "We specifically focused on three enzymes reported to be involved in the immune response to bacterial infections: USP10, UCH-L5, and USP25." (PMID 37841261, 2023). "USP25 can promote the intestinal inflammatory response during bacterial infection, and the goblet cells and Paneth cells in USP25WT mice are significantly decreased compared with those in the USP25−/− mice." (PMID 35096833, 2021).
cardiovascular disease (2 papers, 2025). "Recent studies have highlighted the involvement of DUBs such as USP25, JOSD2, and USP28 in cardiovascular diseases." (PMID 40192103, 2025).
neurodegenerative disease (2 papers, 2021). A disorder of the central nervous system characterized by gradual and progressive loss of neural tissue and neurologic function. "Previous studies have focused on the role of USP25 in antiviral immunity and neurodegenerative diseases." (PMID 34249948, 2021). "This indicates that inhibition of USP25 phosphorylation may have a potential role in the treatment of neurodegenerative diseases." (PMID 34177595, 2021). "VRK2 kinase-mediated phosphorylation of USP25 suppressed the deubiquitinating activity of USP25 and stabilized the molecular chaperone TRiC, leading to the aggregation of misfolded proteins in neurodegenerative diseases." (PMID 34177595, 2021).
heart diseases (1 paper, 2025). "Therefore, further exploring the role of USP25 in MI/RI can systematically reveal its protective effect and enhance the potential of USP25 as a target for the treatment of heart diseases." (PMID 39985261, 2025).
infectious disease (1 paper, 2021). A disorder directly resulting from the presence and activity of a microbial, viral, or parasitic agent in humans. "In addition, USP25 is involved in the processes by which toll-like receptors (TLR) monitor and recognize a variety of different disease-associated molecular patterns and provide the first barrier of the body against infectious diseases." (PMID 34249948, 2021).
USP25 also shares sentences with these, for which no sentence is quoted: non-small cell lung carcinoma (4 papers); multiple sclerosis (2); neurological diseases (2); allergic rhinitis (1); dysplasia (1); emphysema (1); fibrosis (1); inflammation (1); liver cancer (1); lymph node metastasis (1); osteoarthritis (1); osteosarcoma (1); pancreatitis (1); polycystic ovary syndrome (1); Sepsis (1); small intestine (1).